FXR1 (FMR1 autosomal homolog 1)
Description:
mRNA-binding protein that acts as a regulator of mRNAs translation and/or stability, and which is required for various processes, such as neurogenesis, muscle development and spermatogenesis. Specifically binds to AU-rich elements (AREs) in the 3'-UTR of target mRNAs. Promotes formation of some phase-separated membraneless compartment by undergoing liquid-liquid phase separation upon binding to AREs-containing mRNAs, leading to assemble mRNAs into cytoplasmic ribonucleoprotein granules that concentrate mRNAs with associated regulatory factors (By similarity). Required to activate translation of stored mRNAs during late spermatogenesis: acts by undergoing liquid-liquid phase separation to assemble target mRNAs into cytoplasmic ribonucleoprotein granules that recruit translation initiation factor EIF4G3 to activate translation of stored mRNAs in late spermatids (By similarity). Promotes translation of MYC transcripts by recruiting the eIF4F complex to the translation start site. Acts as a negative regulator of inflammation in response to IL19 by promoting destabilization of pro-inflammatory transcripts. Also acts as an inhibitor of inflammation by binding to TNF mRNA, decreasing TNF protein production (By similarity). Acts as a negative regulator of AMPA receptor GRIA2/GluA2 synthesis during long-lasting synaptic potentiation of hippocampal neurons by binding to GRIA2/GluA2 mRNA, thereby inhibiting its translation (By similarity). Regulates proliferation of adult neural stem cells by binding to CDKN1A mRNA and promoting its expression (By similarity). Acts as a regulator of sleep and synaptic homeostasis by regulating translation of transcripts in neurons (By similarity). Required for embryonic and postnatal development of muscle tissue by undergoing liquid-liquid phase separation to assemble target mRNAs into cytoplasmic ribonucleoprotein granules. Involved in the nuclear pore complex localization to the nuclear envelope by preventing cytoplasmic aggregation of nucleoporins: acts by preventing ectopic phase separation of nucleoporins in the cytoplasm via a microtubule-dependent mechanism. Plays a role in the stabilization of PKP2 mRNA and therefore protein abundance, via its interaction with PKP3. May also do the same for PKP2, PKP3 and DSP via its interaction with PKP1. Forms a cytoplasmic messenger ribonucleoprotein (mRNP) network by packaging long mRNAs, serving as a scaffold that recruits proteins and signaling molecules. This network facilitates signaling reactions by maintaining proximity between kinases and substrates, crucial for processes like actomyosin reorganization.
Synonyms: CMYO9A; CMYO9B; CMYP9A; CMYP9B; FXR1P; MYOPMIL; MYORIBF
Tractability: PROTAC: UniProt records ubiquitination sites on it; ubiquitination databases record sites on it; its protein half-life has been measured.
Gene: Protein-coding gene on chromosome 3 (180,868,141 to 180,982,753, forward strand). Ensembl gene ENSG00000114416.
Subcellular location: Cytoplasm, Cytoplasmic ribonucleoprotein granule; Cytoplasm, Stress granule; Cytoplasm; Cell projection, dendrite; Cell projection, dendritic spine; Cell projection, axon; Nucleus envelope; Postsynapse
Subcellular location (Human Protein Atlas): Cytosol
Pathways (Reactome):
Disease: Signaling by BRAF and RAF1 fusions
Gene Ontology:
Molecular function: molecular condensate scaffold activity; mRNA 3'-UTR AU-rich region binding; mRNA 3'-UTR binding; protein binding; protein heterodimerization activity; protein homodimerization activity; RNA binding; RNA strand annealing activity; translation regulator activity; mRNA binding; nucleic acid binding; ribonucleoprotein complex binding
Biological process: membraneless organelle assembly; mRNA destabilization; muscle organ development; negative regulation of inflammatory response; negative regulation of mRNA catabolic process; nuclear pore complex assembly; nuclear pore localization; positive regulation of miRNA-mediated gene silencing; positive regulation of Rho protein signal transduction; positive regulation of translation; skeletal muscle organ development; animal organ development; apoptotic process; dentate gyrus development; mRNA transport; negative regulation of long-term synaptic potentiation; negative regulation of tumor necrosis factor production; positive regulation of long-term neuronal synaptic plasticity; regulation of circadian sleep/wake cycle, sleep; regulation of mRNA metabolic process; regulation of mRNA stability; regulation of neurogenesis; regulation of synaptic transmission, glutamatergic; regulation of translation at presynapse, modulating synaptic transmission; spermatid development; and 4 more
Cellular component: cytoplasm; cytoplasmic ribonucleoprotein granule; cytoplasmic stress granule; cytosol; membrane; nuclear envelope; intracellular membraneless organelle; neuron projection; nucleolus; nucleus; postsynapse; axon; costamere; dendrite; dendritic spine; glutamatergic synapse; perinuclear region of cytoplasm; presynapse; ribonucleoprotein granule; ribosome
Genetic constraint (gnomAD): Loss-of-function variants: 1 observed, 12.95 expected, observed/expected ratio (o/e) 0.0772, 90% interval 0.026 to 0.37. The upper end of that interval is the gene's LOEUF score, 0.37, which puts it in group 1 of 6, group 1 being the genes least tolerant of losing a copy. Missense variants: 69 observed, 114.26 expected, observed/expected ratio (o/e) 0.6, 90% interval 0.5 to 0.74. Synonymous variants: 51 observed, 39.91 expected, observed/expected ratio (o/e) 1.28, 90% interval 1.02 to 1.61.
Homologues: Orthologues: chimpanzee FXR1 (100% identical), macaque FXR1 (100% identical), dog FXR1 (99% identical), pig FXR1 (99% identical), rabbit FXR1 (99% identical), guinea pig FXR1 (99% identical), rat Fxr1 (99% identical), mouse Fxr1 (98% identical), tropical clawed frog fxr1 (88% identical), zebrafish fxr1 (73% identical), Drosophila melanogaster Fmr1 (38% identical). Paralogues in human: FXR2 (64% identical), FMR1 (58% identical).
Diseases named in the same sentence as FXR1 in open-access papers:
FXR1 is named in the same sentence as 83 diseases in open-access papers, as found by Europe PMC text mining. Sharing a sentence is not in itself a finding about the gene and the disease. The quoted sentences say what the papers report.
fragile X syndrome (14 papers, 2013 to 2025). A genetic syndrome caused by mutations in the FMR1 gene which is responsible for the expression of the fragile X mental retardation 1 protein. "Fxr1 belongs to the same gene family as fragile X mental retardation gene 1 (Fmr1), which is considered the causative gene of fragile X syndrome." (PMID 33463674, 2020). "Mutations on the FXR1 gene lead to fragile X syndrome (FXS), autism, AD, and PD by dysregulating translation of its target genes." (PMID 28811863, 2017). "Interestingly, the fragile X syndrome disease mutation, I304N, fully blocked the interaction between FXR1 and NSP3 (Fig. EV3A)." (PMID 38177924, 2024). "Future work on this previously unrecognized role of FXR1 in R-loop homeostasis may shed light on the mechanisms underlying the genome instability phenotypes associated with Fragile X syndrome and other R-loop associated trinucleotide expansion diseases." (PMID 35666183, 2022). "Here we show novel UPS-related factors: the fragile X mental retardation 1 (FMR1) and Fmr1 autosomal homolog 1 (FXR1) proteins and discs large MAGUK scaffold protein 4 (Dlg4) mRNA, which are associated with Fragile X syndrome, are involved in UPS activity." (PMID 36732356, 2023). "The Fragile X-Related 1 gene (FXR1) is a paralog of the Fragile X Mental Retardation 1 gene (FMR1), whose absence causes the Fragile X syndrome, the most common form of inherited intellectual disability." (PMID 23555284, 2013). "The loss-of-function mutations in the FMRP gene results in fragile X syndrome (FXS), whereas the function of FXR1 and FXR2 remains unknown." (PMID 23554595, 2013). "However, due the causal role in fragile x syndrome, most data are available about loss of FMR1 in neurons while functions of FXR1 and especially FXR2 remain largely unexplored." (PMID 41117937, 2025). "In addition, both FXR1 and FMR1 are mutated in the R-loop associated disease, Fragile X syndrome." (PMID 35666183, 2022). "In this way, we confirmed the interaction of FMR1, FXR1, and FXR2 of the Fragile X syndrome family as well as the E3 ubiquitin ligase MKRN2 with nsp3, both in context of single and nsp3/4 expression." (PMID 37905840, 2023). "Numerous RG/RGG-containing proteins have been implicated in neurological disorders, such as FUS and TAF-15 in ALS, FXR1, and FMRP1 in fragile X syndrome (FSX), SMN in spinal muscular atrophy (SMA), SHANK1 in autism, as well as a plethora of human cancers." (PMID 35203243, 2022).
lung carcinoma (11 papers, 2016 to 2025). "It provides a preclinical basis for the use of cDHPs in the treatment of lung cancer and provides new insights into the FXR1-IL-35 axis signaling pathway as an anti-NSCLC target." (PMID 40259042, 2025). "FXR1 can promote tumorigenesis and prevent senescence in certain types of cancer, such as head and neck squamous cell carcinoma and lung cancer." (PMID 40149453, 2025). "MiR301a-3p is positively regulated by FXR1, stating that the levels of FXR1 protein and miR301a-3p are critical for repressing the tumor suppressor p21 and promoting human oral and lung cancer." (PMID 31940341, 2020). "Some studies have explored the oncogenic property of FXR1 in lung cancer with FXR1 overexpression or amplification." (PMID 28767039, 2017). "FXR1 and miR301a-3p promote oral and lung cancer by decreasing p21 expression." (PMID 38238286, 2024). "Furthermore, our findings also demonstrated that FXR1 targets p21 mRNA destabilization by recruiting miR-301a-3p in both oral and lung cancer cells." (PMID 38709899, 2024). "FXR1 and treatment resistance have been examined in pancreatic, breast, brain, and lung cancer." (PMID 38238286, 2024). "Hence, to determine the molecular basis of high FXR1 protein levels in cancer cells, we used A549 lung cancer cells, which show metastatic phenotype under the treatment of cytokine transforming growth factor-β (TGFβ)." (PMID 38709899, 2024). "Interestingly, a significant rise in p21 levels was also found in PRMT5-inhibited cells, implying that unmethylated FXR1 may be dormant in both oral and lung cancer cells." (PMID 38709899, 2024). "Recent studies provide more clues on the roles of Fxr1 in human tumors, for example, elevated Fxr1 levels are detected in tumor tissues relative to that in normal tissues, and its expression is correlated with patients’ prognosis in lung cancer, breast cancer, head and neck cancer, and oral cancer." (PMID 35565262, 2022). "In addition, whether the requirement for FXR1 in cancer development is specific to HNSCC, or could apply to other tumour types exhibiting FXR1 amplification such as lung cancer, remains to be determined." (PMID 27812105, 2016). "As shown in the survival plot the overexpressed PRMT5 and FXR1 (SD > 1) alone or in combination, lead to poor patient survival in HNSCC and lung cancer patients." (PMID 38709899, 2024). "As a result, we investigated whether silencing PRMT5 and PRMT1 affected FXR1, FXR2 and FMRP levels in oral and lung cancer cells." (PMID 38709899, 2024).
head and neck squamous cell carcinoma (10 papers, 2016 to 2025). A squamous cell carcinoma that arises from any of the following anatomic sites: lip and oral cavity, nasal cavity, paranasal sinuses, pharynx, larynx, and salivary glands. "In head and neck squamous cell carcinoma, the overexpression of FXR1 binds and destroys P21 mRNA, destabilizing it and reducing p21 protein expression to promote tumor cell proliferation." (PMID 37951919, 2023). "Critically, in head and neck squamous cell carcinoma, Fxr1 overexpression correlates with reduced Fbxo4 levels in the absence of mutations or loss of mRNA, suggesting the potential for feedback regulation." (PMID 29142209, 2017). "Here, the authors identify Fxr1 as a substrate of SCFFbxo4 and identify an inherent regulatory feedback loop in head and neck squamous cell carcinoma that results in the bypass of senescence and neoplastic progression." (PMID 29142209, 2017). "FXR1 is overexpressed in head and neck squamous cell carcinoma (HNSCC)." (PMID 31416295, 2019). "A recent observation indicates that FXR1 is a key regulator of tumor progression and is critical for growth of non-small cell lung cancer cell (NSCLC), and head and neck squamous cell carcinoma (HNSCC)." (PMID 27606879, 2016). "Many studies have found that FXR1 overexpression promotes carcinogenesis and inhibits senescence in squamous cell carcinoma (SCC) of the lung and head and neck squamous cell carcinoma (HNSCC), resulting in a poor prognosis and survival." (PMID 38238286, 2024).
schizophrenia (10 papers, 2015 to 2025). A major psychotic disorder characterized by abnormalities in the perception or expression of reality. "Fragile X autosomal homolog 1 (FXR1), a member of the fragile X messenger riboprotein 1 family, has been linked to psychiatric disorders including autism and schizophrenia." (PMID 39753370, 2025). "An interaction between polymorphisms in FXR1 and one of its regulators, glycogen synthase kinase 3β, predicts symptom severity in schizophrenia and bipolar disorder." (PMID 39753370, 2025). "There is strong evidence for both gamma oscillation and PV interneuron dysfunction in FXR1-associated disorders including autism spectrum disorder and schizophrenia." (PMID 39753370, 2025). "Genome-wide association studies (GWAS) have linked SNPs in the FXR1 locus to schizophrenia (Schizophrenia Working Group of the Psychiatric Genomics Consortium, 2014)." (PMID 30087606, 2018). "In contrast to FMR1, FXR1 came out of the shadow after its identification as one of the top 30 potential genetic risk factor for schizophrenia." (PMID 30687136, 2018). "Characterization of the schizophrenia risk allele in the FXR1 locus (rs34796896) has shown it to be in linkage disequilibrium with splicing quantitative trait loci (sQTL) SNP (rs1805564) identified in postmortem human dorsolateral pre-frontal cortex (DLPFC)." (PMID 30687136, 2018). "For example, the RNA binding protein FXR1 encode on chromosome 3q26.33 represents an interesting new candidate among the genetic risks factors for schizophrenia identified by GWAS." (PMID 30687136, 2018). "Genetic variants of the fragile X mental retardation syndrome-related protein 1 (FXR1) have been associated to mood regulation, schizophrenia, and bipolar disorders." (PMID 29706865, 2018). "At this locus, rs1805564 associated with an Alt EX of FXR1 (double-corrected P for sQTL=0.019) is in LD with the index SNP rs34796896 (P for schizophrenia association=6.2 × 10−11) at r2=0.94." (PMID 28240266, 2017). "Genome-wide association studies identified FXR1 as a risk variant for schizophrenia (Schizophrenia Working Group of the Psychiatric Genomics, 2014), and FXR1 mRNA levels are reduced in postmortem brain in some individuals with schizophrenia and bipolar disorders." (PMID 39753370, 2025). "However, variants in the FXR1 locus have been genetically associated with bipolar disorder, schizophrenia, insomnia, and emotional regulation." (PMID 36504683, 2022). "Interestingly, anxiety symptoms are highly comorbid in schizophrenia patients and FXR1 being a risk factor for schizophrenia can represent a potential molecular target to study mood related problems in these patients." (PMID 29706865, 2018). "Additionally, the micro-RNA that is the most significantly associated to schizophrenia Mir137 has been shown to inhibit the expression of the Fxr1 negative regulator Gsk3β by acting on the 3′UTR of the GSK3B mRNA." (PMID 30087606, 2018). "This suggests that a schizophrenia-associated SNP in FXR1 locus may possibly contribute to the disease by affecting alternative splicing." (PMID 30087606, 2018). "FXR1 recently has been identified as a risk factor for schizophrenia and bipolar disorder." (PMID 29706865, 2018). "This makes a strong case for the association of Fxr1 to schizophrenia and D2-mediated signaling." (PMID 30087606, 2018). "However, genome-wide association studies (GWAS) have linked FXR1 to schizophrenia and bipolar disorders, therefore indicating its possible wider roles in mental illnesses." (PMID 29706865, 2018). "Its homologs, FXR1 has been associated with schizophrenia and bipolar disorder in several studies." (PMID 27509095, 2016). "Thus, it is possible that alteration in the nuclear or nucleolar localization of FXR1, regulated by the NoS2 of exon 15, may contribute to increase the risk to develop schizophrenia." (PMID 30687136, 2018).
schizophrenia (continued). "Association between the Gsk3β-Fxr1 pathway and glutamatergic signaling also suggests how it may contribute to emotional regulation in response to mood stabilizers, or in illnesses like mood disorders and schizophrenia." (PMID 29706865, 2018). "Targeted deletion of FXR1 from PV interneurons in mice has been shown to alter cortical excitability and elicit schizophrenia-like behavior." (PMID 39753370, 2025). "Moreover, regulation of FXR1 in mouse parvalbumin interneurons leads to the expression of schizophrenia-like behaviors." (PMID 36504683, 2022). "However, the existing observations would support that FXR1 is one example of a gene for which further investigation of contribution to schizophrenia, DRD2 signaling, and antipsychotics drug responsiveness is warranted." (PMID 30687136, 2018). "Closer examination of each schizophrenia-associated loci revealed four regions (each encompasses NEK4, FXR1, SNAP91 or APOPT1), where the index SNP in GWAS is in strong linkage disequilibrium with sQTL SNP(s), suggesting dysregulation of AS as the underlying mechanism of the association signal." (PMID 28240266, 2017). "Interestingly, genomewide significant hits for schizophrenia also encompass the FXR1 locus (Schizophrenia Working Group of the PGC, 2014)." (PMID 26612855, 2015). "We also suggest that in addition of these older players, a deeper investigation of new GWAS identified schizophrenia risk genes such as FXR1 can provide new prospects that are not clearly engaged in dopamine function while being targeted by dopamine-associated signaling molecules." (PMID 30687136, 2018). "By utilizing the list of sQTL SNPs, we could specify four promising candidate disease susceptibility genes for schizophrenia (that is, NEK4, FXR1, SNAP91 and APOPT1), whose AS are regulated by sQTL SNPs in strong LD with the index SNPs identified in the PGC GWAS." (PMID 28240266, 2017). "It would thus be premature to conclude that changes in FMR1 targets identified in schizophrenia results from altered FXR1 functions since these two proteins are not biologically equivalent." (PMID 30687136, 2018). "Furthermore, human SNPs affecting the expression of GSK3B and FXR1 genes in the human prefrontal cortex were shown to interact and affect emotional stability in controls, negative symptoms and antipsychotic drug responsiveness in schizophrenia, as well as symptom severity in bipolar disorder." (PMID 36504683, 2022).